GPX3 (glutathione peroxidase 3)
Diseases named in the same sentence as GPX3 in open-access papers (continued):
Sharing a sentence is not in itself a finding about the gene and the disease.
selenium deficiency (15 papers, 2013 to 2025). A nutritional deficiency disease resulting from inadequate selenium levels in the body, which can lead to impaired function of selenoproteins essential for antioxidant defense and thyroid hormone metabolism. "Existing studies indicate reduced GPX3 expression in Preeclampsia, with selenium deficiency implicated in pregnancy disorders, including Preeclampsia." (PMID 38628314, 2024). "Selenium deficiency, although rare, can be evaluated by measuring serum selenium concentrations as well as plasma or serum glutathione peroxidase 3 (GPx-3) activity or seleno-protein P levels." (PMID 39275323, 2024). "Four subgroups were defined according to the patient's baseline status, including those with normal kidney function, reduced kidney function, selenium deficiency, and submaximal GPx3 activity." (PMID 38063975, 2023). "The baseline characteristics of these patients included impaired renal function, serum selenium deficiency and submaximal GPx3 activity." (PMID 38063975, 2023). "Both plasma SEPP1 and GPX3 are depressed in selenium deficiency and reach a plateau when they achieve their optimal functional activity." (PMID 24465457, 2014). "Consequently, dysregulation of GPx3 and SelP has been implicated in various pathological conditions related to oxidative stress and selenium deficiency." (PMID 40429666, 2025). "Since selenium plays a permissive role in the activity of GPx3, it could be speculated that, over time, selenium deficiency or increased radical production could cause a dangerous uncompensated status (i.e., an OS condition)." (PMID 40429666, 2025). "In rural Chinese cohorts, in which selenium deficiency and high-sodium diets are prevalent, the interactions between GPX3 variants and lifestyle factors may disproportionately increase oxidative stress." (PMID 41152890, 2025). "Several factors like hyperglycemia, selenium deficiency, polymorphisms in GPx3, aging, and lifestyle influence GPx3 levels, although the exact mechanisms remain unclear." (PMID 38791447, 2024). "While selenium treatment elevated serum selenium and SELENOP concentrations but not GPx3 activity in the full patient cohort, subgroup analyses revealed that GPx3 activity increased in patients with reduced kidney function, selenium deficiency and low to moderate GPx3 activity." (PMID 38063975, 2023). "However, Valenta and colleagues revealed that parenteral selenium supplementation employing only boluses given with 1000 μg selenium on day one followed by 500 μg per day for 14 days restored selenium deficiency and GPx-3 activity in septic patients." (PMID 23372722, 2013). "During times of selenium deficiency, the expression of certain selenoprotein genes such as GPX1, GPX3, and selenoprotein W (SELENOW) are more sensitive and thus downregulated compared with “housekeeping” selenoproteins such as deiodinases (DIOs) and GPX4." (PMID 39270936, 2024). "There were no changes observed in either GPx1 or GPx3 expression in the livers and hearts of foetuses due to maternal selenium deficiency." (PMID 32210049, 2020).
chronic kidney disease (14 papers, 2012 to 2025). Impairment of the renal function secondary to chronic kidney damage persisting for three or more months. "Results from studies in GPx3 knock-out and wild-type mice in a model of surgery-induced chronic kidney disease indicate that GPx3 deficiency contributes substantially to chronic kidney disease-induced cardiac failure/disease." (PMID 39765894, 2024). "A causal relationship between GPX3 and NOX has already been pointed out in the development of chronic kidney disease." (PMID 39594421, 2024). "GPX3 is a valid biomarker for chronic kidney disease, contributing to overall selenium status and affecting systemic oxidative stress." (PMID 31404994, 2019). "It is known from chronic kidney disease that serum Se and extracellular GPx3 activities are declining in proportion to disease severity." (PMID 23056383, 2012). "The identified genes Txnip, Gpx3, Ccn2, Kap, Umod and Ren1 may be useful biomarkers and should be further analyzed with regard to the transition from acute to chronic kidney disease." (PMID 38791453, 2024). "Moreover, knockout of Gpx3 resulted in significant impairment of ventricular function and cardiac fibrosis in a murine model of chronic kidney disease." (PMID 38727290, 2024). "Additionally, transcriptomic analysis of small arteries from hypertensive patients with chronic kidney disease revealed that miR-338-3p targets GPX3." (PMID 38927092, 2024). "Similarly, the increased expression levels of GPX3 and 6 in treated groups can be supported by the increases ROS levels and glutathione peroxidase activity on chronic renal failure and renal acidosis." (PMID 33802660, 2021). "Moreover, when GPX3-/- knock-out mice were exposed to surgery-induced chronic kidney disease (CKD), these mice displayed decreased left ventricular fractional shortening, increased platelet aggregation, and microthrombi in the myocardium." (PMID 32781581, 2020).
Insulin resistance (14 papers, 2020 to 2025). Increased resistance towards insulin, that is, diminished effectiveness of insulin in reducing blood glucose levels. "We have previously shown that feeding C57BL/6N mice a selenite-enriched high-fat diet (SRHFD) prevented the diet-induced development of insulin resistance and loss of IR expression in adipose tissue, which was linked to elevated local GPx3 levels in WAT." (PMID 35624726, 2022). "Thus, decreasing GPx3 expression caused insulin resistance in 3T3-L1 preadipocytes with decreased IR expression." (PMID 35624726, 2022). "Previous in vivo and in vitro experiments have demonstrated that GPX3 plays a protective role against insulin resistance, inflammation and adipose dysfunction." (PMID 40895323, 2025). "On the contrary, with dysregulation of GPX3 potentially impacting insulin receptor functionality and contributing to insulin resistance." (PMID 38927092, 2024). "Cultivating 3T3-L1 pre-adipocytes in palmitate-containing medium followed by Se treatment attenuates insulin resistance with enhanced GPx3 and IR expression and adipocyte differentiation." (PMID 35624726, 2022). "GPx3 overexpression in adipocytes ameliorates hyperglucose-induced insulin resistance and diminished expression of inflammatory genes, while GPx3 neutralization in adipocytes enhances expression of pro-inflammatory genes." (PMID 35548052, 2022). "Conversely, feeding lean mice a SRHFD to enhance selenoprotein synthesis protected against the development of diet-induced insulin resistance and increased GPx3 and IR expression in WAT." (PMID 35624726, 2022). "Notably, previous research indicates that miR-196a, by downregulating glutathione peroxidase 3 (GPx3), contributes to insulin resistance (IR)." (PMID 38791447, 2024). "In addition, Rha treatment modulated insulin resistance and increased gene expression of antioxidant enzymes (Cat, Sod2, Gpx3, Mgst1, Prdx3, Gsta4, Gsr, and Sod1) in the ovaries of the PCOS rats." (PMID 35663203, 2022). "The trace element selenium, as a crucial part of antioxidative selenoproteins, can protect against the development of diet-induced insulin resistance in white adipose tissue (WAT) by increasing glutathione peroxidase 3 (GPx3) and insulin receptor (IR) expression." (PMID 35624726, 2022). "Thiazolidinediones (TZDs), by activating PPAR, induce GPX3 expression, which in turn reduces extracellular H2O2 levels and modulates insulin resistance." (PMID 38927092, 2024). "For instance, elevated circulating levels of fatty acid-binding protein 4 (FABP4) and glutathione peroxidase 3 (GPX3) were associated with declining insulin secretion, independent of insulin resistance." (PMID 40768044, 2025). "Recently, Gpx3 has been identified as a novel regulator of insulin receptor expression, and Gpx3 dysregulation would impact insulin receptor and lead to insulin resistance, a not uncommon feature in PAH patients." (PMID 34803695, 2021). "Furthermore, overexpression of GPX3 in adipocytes significantly reduced the expression of pro-inflammatory genes such as SAA3, resistin and CCR2 induced by high glucose levels and attenuated hyperglycemia-induced insulin resistance." (PMID 38927092, 2024).
melanoma (14 papers, 2018 to 2025). A malignant, usually aggressive tumor composed of atypical, neoplastic melanocytes. "Furthermore, induced GPX3 expression in melanoma cells causes a metabolic shift towards oxidative phosphorylation and away from glycolysis, while also negatively regulating both HIF1-α and HIF2- α due to decreased stabilization in the relative absence of ROS." (PMID 35326683, 2022). "Overexpression of glutathione peroxidase 3 inhibited the viability of human melanoma A375 cells and tumor growth." (PMID 37892173, 2023). "Overexpression of GPX3 decreased the viability of melanoma cells and inhibited their growth in a xenografts model." (PMID 35326089, 2022). "In that same study, it was also determined that GPX3 overexpression inhibits melanoma proliferation, and silencing GPX3 expression had the inverse effect on proliferation while promoting a more invasive phenotype." (PMID 35326683, 2022). "Interestingly, GPX3 seems to be downregulated in both melanoma cell lines and tissues due to promoter region hypermethylation." (PMID 35326683, 2022). "Interestingly, our analysis of COL1A2 and GPX3—previously reported to be hypermethylated in melanoma—in the four patient-derived sets of melanoma and melanocytes showed completely different results." (PMID 30719424, 2018). "Among these, we detected co-upregulated melanoma marker gene MLANA and metabolic genes FASN, GPX3, and APOD, suggesting metabolic reprogramming as a key factor in invasiveness." (PMID 40866912, 2025). "In recent years, the role of GPX3 in oxidative stress has been reported, for example: GPX3 can inhibit the expression of HIF1-α by regulating ROS, thereby inhibiting the growth of melanoma cells." (PMID 36937839, 2023). "In melanoma cell lines (A375, SK-MEL-1, SK-MEL-2, and SK-MEL-24), it was found that the mRNA and protein expressions of glutathione peroxidase 3 were significantly lower than that in normal human skin melanocyte PIG1 cells." (PMID 37892173, 2023). "According to our analysis, 66% of the isoforms presented differential expression on melanoma progression: NOS2, SOD1, NOX4, PRX3, PXDN and GPX1 are increased during melanoma progression, while CAT, GPX3, TXNIP, and PRX2 are decreased." (PMID 35326089, 2022). "The antitumor effects of GPx3 were also shown to be elicited by inhibiting HIF-1α and HIF-2α in melanoma cells as a consequence of increased ROS scavenging by GPx3." (PMID 32781581, 2020). "Besides, iNOS, SOD1, NOX4, PRX3, PXDN and GPX1 are generally increased during melanoma progression, while CAT, GPX3, TXNIP and PRX2 are decreased." (PMID 35326089, 2022).
lymph node metastasis (13 papers, 2012 to 2025). "However, GPX3 expression is associated with higher stage and lymph node metastasis, as well as poorer prognosis." (PMID 36845676, 2023). "In COAD, GPX3 expression is associated with T-, N-, M-stage, and lymph node metastasis." (PMID 36845676, 2023). "Similarly, in STAD, we used univariate analysis to find that higher GPX3 expression (p = 0.008; HR = 1.533), M1 stage (p = 0.014; HR = 2.052), N1-3 stage (p = 0.004; HR = 1.783), lymph node metastasis (p = 0.002; HR = 1.933) were risk factors for OS." (PMID 36845676, 2023). "In BRCA, we used univariate analysis to find that risk factors for OS included higher GPX3 expression (p = 0.0170; HR = 1.410), M1 stage (p = 0.009; HR = 1.681), N1-3 stage (p < 0.001; HR = 2.285), T4 stage (p < 0.001; HR = 3.220), and lymph node metastasis (p < 0.001; HR = 2.208)." (PMID 36845676, 2023). "In PRAD, GPX3 expression is associated with T-, M-stage, lymph node metastasis, and recurrence." (PMID 36845676, 2023). "Furthermore, Chi square test revealed that low expression of GPX3 was significantly negatively correlated with ER/PR expression and positively linked to tumor size, histopathological grade and lymph node metastasis." (PMID 32782436, 2020). "disclosed that GPX3 methylation in GC was associated with lymph node metastasis." (PMID 27891827, 2017). "This is in accordance with our findings showing a significant correlation of GPX3 downregulation and hypermethylation with lymph node metastasis." (PMID 23071548, 2012). "Based on the available clinicopathological information, we found both GPX3 hypermethylation and downregulation of GPX3 expression significantly correlated with lymph node metastasis (P = 0.029 and P = 0.018 for DNA methylation and gene expression, respectively)." (PMID 23071548, 2012). "Overall, patients with high GPX3 expression and low GPX3 expression in COAD, PRAD, KIRC, LUAD, and STAD showed differences in T-, N-, and M-stage, lymph node metastasis, and occurrence of recurrence." (PMID 36845676, 2023). "We compared the relationship between GPX3 expression level and the presence or absence of lymph node metastasis." (PMID 36845676, 2023). "According to clinicopathologic characteristics, we identified that CRYAB, ECM1, GPX3, and CGNL1 may predict histological grade, UICC stage and lymph node metastasis." (PMID 32292720, 2020). "GPX3 DNA copy number did not correlate with lymph node metastasis and other parameters, possibly due to the small number of samples." (PMID 23071548, 2012). "Since almost all IBC patients presented with positive axillary lymph node metastasis, herein, we investigated whether expression and epigenetic regulation of GPX3 may contribute to the aggressive phenotype IBC versus non-IBC." (PMID 24790704, 2014).
thyroid cancer (13 papers, 2014 to 2025). "Compared to adjacent normal tissues, GPX3 expression was significantly lower in the clinical thyroid cancer samples." (PMID 40092686, 2025). "To further validate our findings, we performed immunohistochemical staining for GPX3 on 58 paired thyroid cancer (TC) and adjacent normal tissue samples, followed by scoring." (PMID 40092686, 2025). "Plasma proteomic studies have found that LCAT, GPX3, and leukotriene b4 can serve as potential biomarkers for thyroid cancer, and serum ISG15 and PLXNB2 can also serve as potential biomarkers." (PMID 40265010, 2025). "Third, glutathione peroxidase 3 (GPX3), a selenoprotein, suppressed the metastasis of thyroid cancer by inhibiting the Wnt/β-catenin signaling pathway." (PMID 38027150, 2023). "For example, GPX3 is a Category 2 protein where suppression directly correlates with promotion of metastasis in human thyroid cancer, and the Category 1 protein, BAX has been reported to be upregulated in relation to papillary thyroid cancer." (PMID 32092871, 2020). "In human thyroid cancer, GPx3 is frequently methylated, and the expression of GPx3 is regulated by methylation of the promoter region, and this methylation is related to tumor size and lymph node metastasis through the inhibition of Wnt/β-catenin signaling." (PMID 32571353, 2020). "A low expression of GPX3 was found to be a biomarker for poor prognosis in gallbladder cancer, and silencing GPX3 was found to promote tumor metastasis of thyroid cancer in which GPX3 functioned as a TSG." (PMID 29875348, 2018). "Insufficient selenium levels might contribute to a reduction in GPX3 levels, thereby facilitating the metastasis of thyroid cancer." (PMID 38027150, 2023). "On the other hand GPx3 is negatively correlated with MAPK oncogenic signaling pathway, which suggests a potential antitumor effect in thyroid cancer, while a decrease in GPx3 levels predisposes to an increase in the size of primary tumors and the number of metastatic lymph nodes." (PMID 37033262, 2023). "Glutathione peroxidase family showed variable gene expression: GPX1 and GPX2 expression analysis suggested minor increase in mRNA synthesis, GPX3, GPX5, and GPX7 expression was downregulated in thyroid cancers, whereas GPX4 expression did not change." (PMID 26664298, 2015).
colon cancer (10 papers, 2014 to 2024). "Decreased systemic GPx3 levels have been shown to promote colon tumor initiation and carcinogenic stimuli in animal studies." (PMID 34836325, 2021). "It is reported that GPX3 is related to many malignancies including including head and neck, ovarian, and colon tumors." (PMID 32292720, 2020). "Knockdown of GPX3 in the human colon cancer cell line Caco2 resulted in increased ROS production and DNA damage." (PMID 25970749, 2015). "The GPX3 gene increased the sensitivity of cell lines to bisacodyl active ingredient (for treating glioblastoma) and also increased the tolerance to okadaic acid (for treating colon cancer)." (PMID 33706760, 2021). "Moreover, several reports demonstrated that the tumor suppressive function of GPx3 was mediated through induction of apoptosis in prostate and colon cancer." (PMID 25333265, 2014). "In our study, eight proteins including G6PD, GPX3, and LAP3 which are reported to be involved in colon cancer cell growth were connected to glutathione metabolism." (PMID 34386520, 2021).
Hyperglycemia (10 papers, 2014 to 2025). An increased concentration of glucose in the blood. "Oxidative stress, evaluated via GPX3, was the only biomarker significantly predicted by blood glucose levels (R2 = 0.239, p = 0.010), highlighting the link between hyperglycemia and redox imbalance." (PMID 40299518, 2025). "The upregulated levels of GPX-3 in the cardiac tissue of diabetic mice have been demonstrated to protect cardiomyocytes against hyperglycemia-induced oxidative stress." (PMID 36553589, 2022). "We assessed the relationship between another extracellular selenoprotein GPX3 and future hyperglycemia." (PMID 30425271, 2018). "Moreover, GPX3 belongs to an adipokine cluster related to insulin sensitivity/hyperglycemia and lipid metabolism in humans." (PMID 35624726, 2022). "Likewise, the differences observed for GPX3 and HRG could stem from the challenges created by hyperglycaemia." (PMID 37537394, 2023).